TMPRSS2 (transmembrane serine protease 2)
Diseases named in the same sentence as TMPRSS2 in open-access papers (continued):
Sharing a sentence is not in itself a finding about the gene and the disease.
infection (continued). "In this study, experimental infection with a mouse-passaged strain and N501Y-carrying variants of SARS-CoV-2, including Beta, Gamma and Omicron, revealed that deficiency of TMPRSS2 caused minimal viral growth and induced no pathological lesions in the lungs." (PMID 36243815, 2022). "In most cases, TMPRSS2 enhances SARS-CoV-2 infection in vitro, but these results do not prove that TMPRSS2 is used in actual infection or that it is involved in pathogenesis." (PMID 36243815, 2022). "Pseudovirus infection of both VeroGFP and VeroTMPRSS2 cells were significantly increased by factor Xa, indicating that factor Xa enhancement of infection is not dependent on TMPRSS2." (PMID 35294338, 2022). "We further knocked down IFITM3 in TMPRSS2-positive Calu-3 cells, and did not observe any effect on infection of SARS-CoV-2 S-pseudotyped virus." (PMID 36423162, 2022). "The infection begins when the virion binds the angiotensin-converting enzyme 2 (ACE2) receptor to interact with the spike protein (S protein) and TMPRSS2, a protease that cleaves the S protein to release its domains, which is an essential step in viral infection to enter the host cell." (PMID 35456120, 2022). "Notably, infection of A549-ACE2, A549-ACE2/TMPRSS2 and Calu3 cells using an MOI 2 led to a significant phosphorylation of ERK1/2 1 h.p.i." (PMID 35013790, 2022). "Notwithstanding, MβCD, which was shown to abrogate entry of pseudovirus and cell-cell fusion, did not inhibit the infection of ACE+/TMPRSS2+ A549 cells by a clinical isolate of SARS-CoV-2." (PMID 35562967, 2022). "Furthermore, lung macrophages express the main receptor for the virus and viral spike-priming protease necessary for infection (ACE2 and TMPRSS2)." (PMID 35708858, 2022). "The improved protection against proteolytic premature activation of VOC Alpha spike may be particularly beneficial for infection of cells expressing low ACE2 and TMPRSS2 levels, as represented by NCI-H1299 cells." (PMID 36383605, 2022). "Substantive research has explored the role of key genetic markers in the infection of Angiotensin‐Converting Enzyme 2 (ACE2) and Transmembrane serine protease 2 (TMPRSS2), though these sources of diversity have not exposed notable polymorphic attributes to protect the susceptible." (PMID 35574521, 2022). "Typically, the receptor-binding domain (RBD), which is found on the surface of SARS-CoV-2, binds to human angiotensin-converting enzyme 2 (ACE2), whereas transmembrane serine protease 2 (TMPRSS2) is a protease important for S proteolytic processing and priming during infection." (PMID 34202613, 2021). "The S-glycoprotein cleavage TMPRSS2 enzyme potentiates SARS- and MERS-CoVs infections." (PMID 34122058, 2021). "Infection with 60 ng/ml of HIV-1 for 24 h or 48 h did not result in any changes in the expression of ACE2 or TMPRSS2 at the mRNA (respectively) or protein levels in these cells." (PMID 34325716, 2021). "Furthermore, in Calu3 cells and over-expressing TMPRSS2 cells, SB treatments inhibited the SARS-CoV-2 Vpp infection." (PMID 34063247, 2021). "Although Fiege and colleagues did not recognize basal cell infection, and also did not identify TMPRSS2 transcripts in basal cells, the potential for expansive infection deserves further consideration." (PMID 33901166, 2021). "HCE-2 corneal epithelial cells were also investigated due to the proposed role of the ocular surface as a route of infection but little or no ACE2 or TMPRSS2 expression was detected." (PMID 34200372, 2021). "RaTG13 S-mediated VSVpp infection of A549 cells was equally effective in the presence or absence of TMPRSS2." (PMID 34824253, 2021). "Infection sensitivities of various cell types did not correlate with mRNA abundance of hACE2, TMPRSS2, or TMPRSS4." (PMID 34064066, 2021). "In Ad-ACE2-transduced mice lacking TMPRSS2, SARS-CoV-2 growth is inhibited, implying that the TMPRSS2-mediated pathway is a key component of pathogenic infection in vivo." (PMID 34960703, 2021).
infection (continued). "TMPRSS15 shares high homology in the serine protease domains of TMPRSS2, thus, may participate in the cleavage of the S protein of SARS-CoV-2 during infection." (PMID 34335974, 2021). "This is consistent with the finding that a target cell needs to express TMPRSS2 to be infected, but altering expression of TMPRSS2 in the infected cell does not affect the efficiency of infection." (PMID 33466921, 2021). "Therefore, infection with SARS-CoV-2 appears to parallel the levels of ACE2 expression, although the expression of TMPRSS2 and other receptors are also likely to contribute to SARS-CoV-2 infectivity." (PMID 33419885, 2021). "Recent data show that cleavage into S1/S2 subunits by TMPRSS2 is not a prerequisite for infection, as the virus can use alternatively the endocytic pathway." (PMID 33467029, 2021). "The infection site of the SARS-CoV-2 correlates with the coexpression sites of ACE2 and TMPRSS2." (PMID 34336361, 2021). "Cells naturally expressing the ACE2 receptor and the transmembrane serine protease 2 (TMPRSS2) are then added to the plates and incubated for 48–72 h otherwise co-transfection of ACE2 and TMPRSS2 plasmids can be carried out to render cells such as HEK 293T, and HeLa permissive to infection." (PMID 33738456, 2021). "Since the receptors ACE2 and TMPRSS2, which are utilized by SARS-CoV-2, were not co-expressed in the placenta, we postulate that it is extremely rare for SARS-CoV-2 to cause infection through ACE2/TMPRSS2 route, thus its impact on the fetus is negligible." (PMID 33613576, 2021). "The authors observed that NRP-1 only with the coexpression of ACE-2 and/or TMPRSS2 enhanced infection of coronavirus, as opposed to NRP-1 alone." (PMID 34202613, 2021). "In contrast to the results for RVAs, T2T11D cells were resistant to infection by immature SeV virions, consistent with previous findings that TMPRSS2 has no ability to activate immature SeV virions at the entry step." (PMID 33762412, 2021). "Since the receptors, ACE2 and TMPRSS2, utilized by SARS-CoV-2 are not co-expressed in the placenta, so it is extremely rare for SARS-CoV-2 to cause infection through this route and the impact on the fetus is negligible." (PMID 33613576, 2021). "One possibility is a different expression of angiotensin-converting enzyme 2 (ACE-2), which represents the SARS-CoV-2 receptor, and transmembrane protease serine 2 (TMPRSS2), which activates the structural spike protein of SARS-CoV-2 for membrane fusion and enables cell infection." (PMID 34742332, 2021). "Initially, SARS-CoV-2 mediated infection is dependent on the viral S1 domain binding to ACE2 and their cleavage by the transmembrane serine protease 2 (TMPRSS2), whereas the viral S2 domain is responsible for conformational changes that drive the fusion process between viral and host cell membranes." (PMID 33791232, 2021). "It came as surprise, however, that overexpression of TMPRSS2 only enhanced VSVpp infection mediated by the SARS-CoV-2 but not by the RaTG13 T403R S protein since the S2′cleavage site that is targeted by TMPRSS2 is identical in these S proteins." (PMID 34824253, 2021). "Note that the lack of correlation of hACE2 mRNA with infection of different cell types was not due to the abundance of TMPRSS2 and TMPRSS4, which prime SASR-CoV-2 spike proteins for hACE2-dependent viral entry." (PMID 34064066, 2021). "In summary, we find that the expression of ACE2 and TMPRSS2 are indicative but not sufficient for SARS-CoV-2 productive infection in human cell lines, probably partly due to a truncated ACE2 splice variant and TMPRSS2 variants." (PMID 34339474, 2021). "The infection of lung cells by SARS-CoV-2 is mediated by the binding to the cellular angiotensin-converting enzyme II (ACE2) receptor and the priming of the viral S protein by transmembrane serine protease 2 (TMPRSS2)." (PMID 34960648, 2021).
infection (continued). "Cathepsins inhibitor E64d treatment absolutely inhibited the infection of WT, D614G, N501Y.V1 and N501Y.V2 RBD pseudoviruses into 293T-hACE2 cells, indicating that CatB/L is the dominant proteases required for priming of SARS-CoV-2 S protein in TMPRSS2- cells." (PMID 34722330, 2021). "In addition, co-expression of ACE2 and TMPRSS2 was detected in more than 50% of Wolfring’s gland cells in the cat eyelid and epicardial cells in the cat heart, suggesting the possibility that such tissue could act as a putative portal for the initial infection and transmission of SARS-CoV-2." (PMID 34873160, 2021). "The TMPRSS2 increase by fluoxetine was detected in both non-infected and infected cells suggesting that the infection alone has no impact on this event." (PMID 35126106, 2021). "It allows the infection of target cells by binding to the human angiotensin-converting enzyme (ACE2) receptors, among others, which triggers proteolysis by transmembrane protease serine 2 (TMPRSS2), furin, and perhaps other proteases, leading to virion and host cell membrane fusion." (PMID 33800932, 2021). "The IC50 values varied depending on the form of infection and cell lines used, ranging from 1.4–5 μg/mL iota-carrageenan in the SSPL particles system to 2.1–10.3 μg/mL in A549-ACE2/TMPRSS2 cells, and 0.04–0.15 μg/mL in Calu-3 human lung cells infected with the SARS-CoV-2 variants." (PMID 34947999, 2021). "Indeed, mechanistic studies have shown that a clinically approved TMPRSS2 inhibitor, camostat mesylate, inhibited SARS-CoV-2 S-driven infection in vitro." (PMID 33869309, 2021). "Thus, the rapid spread of communal infection is reliant on the efficiency of the ACE2-spike interaction and TMPRSS2 protease activity." (PMID 34063247, 2021). "We have studied twenty-four different hUC-MSCs cell lines and have determined levels ACE2 and TMPRSS2 therein with several techniques, leading to our robust conclusion of no ACE2 expression and low TMPRSS2 infection in Wharton's jelly-derived hUC-MSCs." (PMID 33853637, 2021). "However, due to very low level expression of both hACE2 and transmembrane protease serine 2 (TMPRSS2), two major host factors that mediate SARS-CoV-2 cellular entry, HEK293T cells exhibit a very low rate of infection by SARS-CoV-2." (PMID 34433867, 2021). "Infection of cells by SARS-CoV-2 is dependent on the expression of the binding receptor ACE2 (Angiotensin-converting enzyme 2) and the fusion priming protease TMPRSS2 (Transmembrane protease, serine 2)." (PMID 34745122, 2021). "Like NCOA7, BafA1, E64d or Niclosamide treatment potently inhibited infection with Spike pseudotype in the absence of TMPRSS2, however, TMPRSS2 overexpression attenuated the inhibitory effects of each of these inhibitors." (PMID 34807954, 2021). "For the Sdel virus, E-64d significantly inhibited infection in Vero, Vero-TMPRSS2, and A549-ACE2 cells, whereas camostat did not reduce the infection, even in Vero-TMPRSS2 cells." (PMID 33574281, 2021). "Upon human infection with SARS-CoV-2, the S protein binds to ACE2 receptor on the cell surface, followed by priming by a host proteinase, the most important of which is transmembrane serine protease 2 (TMPRSS2), to stimulate viral entry into the host cell." (PMID 34408749, 2021). "In the absence of tet to induce LY6E, expression of TMPRSS2 significantly enhanced the infection of SARSpp, SARS-CoV-2pp, MERSpp, and 229Epp, but not the infection of other human CoVpp and LASVpp." (PMID 32641482, 2020). "Interestingly, while neuropilin-1 alone promotes SARS-CoV-2 entry and infection, its coexpression with ACE-2 and TMPRSS2 markedly potentiates this effect." (PMID 33584720, 2020). "Our study is a proof of concept that new molecules recognized or regulated by the SARS-CoV-2, specifically TMPRSS2 and IFITM3 may be related to infection and anti-viral effect, respectively." (PMID 33061814, 2020).
infection (continued). "In addition to ACE2 and TMPRSS2, other potential SARS-CoV-2 receptors, proteases and cofactors for infection have been suggested, including BSG (CD147) and NRP1 as receptors, and CTSL as a key protease." (PMID 32750256, 2020). "Important data show that the TMPRSS2 is not necessary for the development and homeostasis and so it is potentially and sensible pharmacological target able to inactivate the infection." (PMID 33142764, 2020). "Cell culture infection tests demonstrated that SARS‐CoV‐2 uses two proteases for this proteolytic processing, either the lysosomal cathepsin CatB/L or the transmembrane protease TMPRSS2." (PMID 32573950, 2020). "Similarly, an FDA-approved mucolytic cough suppressant, Bromhexine hydrochloride (BHH), inhibits TMPRSS2 (IC50 0.75 μM) and hence blocks infection of CoV and influenza virus." (PMID 32604730, 2020). "Knowledge about the expression of ACE2 and TMPRSS2, as well as other potential entry genes of SARS-CoV-2, namely FURIN, DPP4, and BSG, is extremely important to understand the infection of SARS-CoV-2 and to find ways to prevent the infection." (PMID 33081421, 2020). "Absence of TMPRSS2 affected the infection sites and virus spread within the respiratory tract; therefore, this is a useful model for COVID-19 research." (PMID 32983181, 2020). "This review has concentrated on the prevailing hypothesis that an essential first step in infection is SARS‐CoV‐2 binding to ACE2 and for TMPRSS2 to prime the viral spike protein." (PMID 32358833, 2020). "Furthermore, we compared the promotion effect of Vero/TMPRSS2 and Vero/MSPL cell lines on PEDV isolates (2013-A and NJ) by detecting cytopathic effects and fluorescence intensity post-infection." (PMID 32471322, 2020). "In addition to ACE2 and TMPRSS2, other potential SARS-CoV-2 receptors, proteases and cofactors for infection have been suggested, including BSG (CD147) and neuropilin-1 (NRP1)." (PMID 33380340, 2020). "Evidence supported that transmembrane protease serine 2 (TMPRSS2) could promote SARS-CoV-2 migration and infection by preactivating S-protein and cleaving ACE2." (PMID 33363165, 2020). "On the other hand, the amount of virus or receptor expression necessary to cause infection is not known; however, currently, the eye is not considered to be a high-risk tissue due to the low ACE2 and TMPRSS2 expression." (PMID 33469546, 2020). "Furthermore, after PEDV isolates 2013-A and NJ infection, syncytium (cell-cell fusion) in Vero/TMPRSS2, Vero/MSPL and Vero cells adding trypsin expanded with time, suggesting that TMPRSS2 and MSPL contribute to the PEDV infection." (PMID 32471322, 2020). "Infection requires that the receptor binding domain (RBD) S1 binds to the host cell receptor, and that site S2 undergoes proteolytic cleavage by Furin protease and/or transmembrane protease serine 2 (TMPRSS2)." (PMID 33551727, 2020). "By contrast, TMPRSS2 was shown to enhance viral entry and replication of MERS-CoV, although the peak titers of the recombinants in Vero/TMPRSS2 cells were similar, with a slight delay in replication in the Amibara S recombinants at 1-day post-infection." (PMID 31275264, 2019). "At 72 h post-infection, viral RNA levels in Vero cells expressing MSPL were significantly higher than those in the other groups, and the viral mRNA relative quantity in trypsin-treated cells was slightly higher than that in TMPRSS2-transfected cells." (PMID 28524070, 2017). "However, the efficacy of TMPRSS2 in activating PEDV replication was almost the same as that of 3 μg/mL trypsin and was higher than that of HAT or DESC1 at 84 h post-infection." (PMID 28524070, 2017). "Thus, epithelial cell-expressed TMPRSS2, which critically contributes to the lung pathology in SARS-CoV-2 infection, emerges as an intestinal incretin regulator and a potential link between infection and chronic cardiometabolic diseases." (PMID 41842964, 2026).
infection (continued). "However, in this study, inhibition of TMPRSS2 activity with camostat did not suppress viral entry or infection, indicating that TMPRSS2 was not required for BCoV-mediated membrane fusion." (PMID 41251346, 2025). "Furthermore, it has been noted that CQ does not inhibit infection with SARS-CoV-2 in the TMPRSS2-expressing human lung cell line Calu-3." (PMID 40535766, 2025). "Furthermore, the role of the H655 residue in mediating the TMPRSS2 interaction with the SARS-CoV-2 spike protein and the affinity between the TMPRSS2 and spike affect the infection pathway via the cell membrane, potentially reducing the utilization of the endosomal route for viral entry." (PMID 39858469, 2025). "Furthermore, cRIP-seq analysis identified two additional NSP9 binding sites at positions 77 and 78 on the negative-sense RNA, observed during infection in Vero E6 TMPRSS2 cells but not previously reported in A549 cells." (PMID 41472274, 2025). "Reduced TMPRSS2 may mitigate early infection but is unlikely to fully explain outcomes, especially in later inflammatory phases." (PMID 41150771, 2025). "However, other cathepsin L inhibitors prevented infection of cells lacking TMPRSS2 when those were incubated with inhibitors prior to SARS-CoV-2 infection." (PMID 38381158, 2024). "Moreover, the TMPRSS2 inhibitor Camostat did not impair infection in IGROV-1 but was active in Vero E6 TMP-1 cells, confirming the absence of TMPRSS2 in IGROV-1 cells." (PMID 38480689, 2024). "So, when a reduced TMPRSS2 expression is observed while Omicron is carrying out the infection, the non-utilization of the protease could be a contributing factor to this reduction." (PMID 39597701, 2024). "However, the mutation rate in Vero cells was not higher than in Vero/TMPRSS2 cells, suggesting that TMPRSS2 contributed little to HPIV2 infection of the cells." (PMID 39078148, 2024). "Furthermore, this alternative infection pathway may contribute to the clinical finding that Omicron typically causes milder illness, as it preferentially infects and replicates in the upper airways above the lungs and does not infect TMPRSS2-rich lung cells compared to other variants." (PMID 39347199, 2024). "Instead, SARS-CoV S could employ several other trypsin-like serine proteases for functional activation, and used cathepsin-mediated late entry during infection when TMPRSS2 was absent." (PMID 39599912, 2024). "To better enable understanding of both acute (<14 dpi) and post-acute (>14 dpi) infection phases, we describe the development and characterization of a novel non-lethal KI mouse that expresses both the ACE2 and transmembrane serine protease 2 (TMPRSS2) genes (hACE2/hTMPRSS2)." (PMID 39050847, 2024). "These matrix metalloproteases are also known to be involved in viral life cycles; thus, even when TMPRSS2 does not have a direct interaction with the virus, it may still affect the outcome of infection through other mechanisms." (PMID 38932275, 2024). "Several transmembrane proteases, including ADAM17, transmembrane serine protease 2 (TMPRSS), and tumor necrosis factor (TNF)-converting enzyme, along with proteins like vimentin and clathrin are believed to play roles in the comprehensive process of establishing infection." (PMID 38339115, 2024). "Recent evidence has shown that this variant favours either endosomal cathepsin- in cell lines or membrane type-matryx metallo proteinases (MT-MMPs) mediated entry rather than TMPRSS2-mediated infection in human nasal epithelial cells grown at Air-liquid interphase (ALI)." (PMID 39541404, 2024). "In case of SARS-CoV-2, infection is, however, facilitated by some structural features of the virus and the fact that it engages angiotensin-converting enzyme 2 (ACE2) as the primary receptor and employs the transmembrane serine protease 2 (TMPRSS2) for protein priming." (PMID 38750098, 2024).